RNU6-940P (RNA, U6 small nuclear 940, pseudogene)
Gene: Small nuclear RNA gene on chromosome 12 (48,975,543 to 48,975,646, forward strand). Ensembl gene ENSG00000200303.
Homologues: Orthologues: chimpanzee U6 (97% identical), macaque U6 (97% identical), rabbit U6 (91% identical), dog U6 (90% identical), guinea pig U6 (89% identical), mouse Gm25518 (89% identical), rabbit U6 (88% identical), dog U6 (86% identical), pig U6 (85% identical), guinea pig U6 (83% identical), rabbit U6 (77% identical), rat LOC120095377 (49% identical), and 1 more. Paralogues in human: RNU6-181P (93% identical), RNU6-434P (93% identical), RNU6-1145P (92% identical), RNU6-16P (92% identical), RNU6-310P (92% identical), RNU6-393P (92% identical), RNU6-480P (92% identical), RNU6-812P (92% identical), RNU6-961P (92% identical), RNU6-1316P (91% identical), RNU6-144P (91% identical), RNU6-20P (91% identical), and 1287 more.